IL13 (interleukin 13)
Diseases named in the same sentence as IL13 in open-access papers (continued):
Sharing a sentence is not in itself a finding about the gene and the disease.
breast carcinoma (continued). "A recent study has shown that macrophages stimulated by IL4 and IL13 promoted invasion of breast cancer cells through Rho-GTPase regulation." (PMID 35207737, 2022). "Another MR study using the same source of instrumental variables investigated 24 cytokines in relation to breast cancer risk and demonstrated positive associations for MCP-1, MIP1b and IL-13." (PMID 35012533, 2022). "The aim of this study was to test the efficacy of QBX258, a monoclonal IL4/IL13 neutralizing antibody, in women with breast cancer–related lymphedema (BCRL)." (PMID 34571811, 2021). "CD4+ T effector cells that express high levels of IL-13 accelerated development of mammary carcinomas and their metastasis to the lung by enhancing pro-tumorigenic potential of tumor-associated macrophages." (PMID 33686176, 2021). "Activation of IL4/IL13 signaling pathways increases breast cancer invasion and propensity for lung metastasis." (PMID 34571811, 2021). "In another breast cancer study, levels of IL-7, IL-8, IL-13, macrophage migration inhibitory factor (MIF), and TNF-β were increased, whereas those of CTACK, G-CSF, HGF, IL-1β, and TNF-α were decreased after IORT exposure." (PMID 34641806, 2021). "Another study demonstrated that high expression of the plasma membrane receptor for IL-13 (IL-13Rα1) was observed in breast cancer patients with HER2 positivity." (PMID 33178603, 2020). "The conditioned medium from M2 macrophages after IL-4/IL-13 induction (M2CM) significantly improved the migration ability of breast cancer 4T1 cells in vitro." (PMID 30766614, 2019). "Our data show that IL-4/IL-13 in vitro differentiated M2a macrophages significantly increase migratory and invasive potential of breast cancer cells at a greater rate than M2b or M2c macrophages." (PMID 31214501, 2019). "Here, we find that IL-4/IL-13 polarized M2a macrophages enhance breast cancer cell migration and invasion at a greater rate than either M2b or M2c macrophages and are thus an important subpopulation to target therapeutically." (PMID 31214501, 2019). "We found only three small molecules, which concentration differs significantly in both luminal A and luminal B subtypes of breast cancer: IL-13, MCP-1 (CCL2), and MCP-3 (CCL7)." (PMID 31861498, 2019). "In this study, our data defines IL-4/IL-13 stimulated macrophages (M2a macrophages) as the strongest inducers of breast cancer cell migration and invasion." (PMID 31214501, 2019). "We tested the IL-13 and TSC1 SNPs for replication of main effects by conducting lookups in genome-wide association study (GWAS) data from the Shanghai Breast Cancer Genetics Study (SBCGS)." (PMID 30601841, 2019). "Breast cancer tumors are infiltrated with CD4+ T cells secreting IFN-γ and IL-13 while breast cancer instructs dendritic cells to prime IL-13-secreting CD4+ T cells that facilitate tumor development." (PMID 30648081, 2018). "The addition of Compound C to metformin-treated breast cancer cells significantly increased the expressions of IL-4, IL-10 and IL-13 when compared to metformin treatment alone." (PMID 28157701, 2017). "Consistent with the RNA expression, protein secretion from the metformin-treated breast cancer cells also showed decreased expressions of IL-4, IL-10 and IL-13 in the medium and an increased expression of IFN-γ." (PMID 28157701, 2017). "Elevated levels of IL-13 were detected in some tumors, such as breast cancer, oral squamous cell carcinoma and colorectal cancer." (PMID 27533463, 2016). "IL-13 which is derived from T-lymphocyte is highly expressed in breast cancer as reported in previous studies and exerts its effect by inducing the up-regulation of VCAM-1 which consequently modulates the angiogenesis event." (PMID 27558166, 2016). "Recent reports show that curdlan can inhibit TH2‐cell responses, promoting breast cancer progression 43; it was also reported to suppress IL‐5, IL‐13 and surprisingly IL‐1β from lymph nodes during epicutaneous sensitization." (PMID 26573878, 2016).
breast carcinoma (continued). "Consistent with the role of TP63 as a suppressor of breast cancer cell migration, the combination of IL13Rα2 depletion concomitant with IL-13 treatment potently suppressed the migratory potential of metastatic MIV cells." (PMID 26208975, 2015). "Initially, we aimed to identify genes which are transcriptionally regulated by IL-13 in breast cancer cells." (PMID 26208975, 2015). "Overexpression of the IL13RA2 chain in human breast cancer cell line and pancreatic cancer cell line inhibited tumor development in nude mice, probably mediated by IL-13." (PMID 25481245, 2014). "In another study, The effects of human IL-4 and IL-13 on clonal growth of breast cancer cells were investigated that revealed IL-13 can reduced clonal growth of 3 cell type." (PMID 23108822, 2012). "For example, breast cancer cells have been shown to produce IL-13 themselves, resulting not only in autocrine STAT6-phosphorylation but also in the instruction of DCs to skew CD4 T cells towards a Th2 phenotype with high production of IL-4 and IL-13." (PMID 22611421, 2012). "Specifically, IL12, IL2 and IFNG, all involved in Th1 mediated immune response, showed strong correlations in both ER+ and ER- breast cancer, while IL13 (involved in a Th2 immune response) was generally anti-correlated to these pathways." (PMID 21050467, 2010). "IL-4 and IL-13, in particular, support breast cancer cell survival, proliferation, and metastasis." (PMID 39456897, 2024). "IL-13-producing ILC2s may further promote immunosuppression from MDSCs during advanced stages of breast cancer metastasis." (PMID 39309440, 2024). "IL-13-producing ILC2s may further promote MDSC-mediated immunosuppression during advanced stages of breast cancer metastasis." (PMID 39309440, 2024). "Indeed, studies have documented that targeting M2 markers (e.g. IL‐4 and/or IL‐13) can reduce primary breast tumor burden and prevent breast cancer metastasis." (PMID 36325601, 2022). "Taken together, our findings suggest that stage-dependent ILC2 activation might induce differential functioning of MDSCs through IL-13/IL-13Rα1 signaling during cancer progression from micro- to macrometastasis in breast cancer lung metastasis." (PMID 35805039, 2022). "Notably, anakinra treatment prevented breast cancer progression with a substantial decrease in the proportion of IL-13 producing tumor-infiltrating CD4+ T cells and a concomitant increase of IFN-γ producing CD4+ T cells in a humanized mouse model." (PMID 33686176, 2021). "In addition, TSLP has been implicated in breast cancer pathogenesis by regulating the DC expression of OX40L, differentiating the Th2 cells, and increasing production of IL13." (PMID 34571811, 2021). "In addition, blocking the IL-13 mediated phosphorylation of STAT6 can protect breast cancer cells from developing sensitivity to irradiation." (PMID 33569004, 2020). "Similarly, high levels of IL4 and IL13 are detected in the tumor micro-environment, peripheral blood of prostate, bladder, and breast cancer patients." (PMID 31540495, 2019). "In conclusion, we replicated an association of SNP rs1800925 in IL-13 with breast cancer risk among women of East Asian descent, and not among women of European descent." (PMID 30601841, 2019). "We report an association between rs1800925 (IL-13) and breast cancer risk among East Asian women, which was not heterogeneous across breast cancer subtypes." (PMID 30601841, 2019). "Similarly, the IL-33/ILC2 axis also accelerates tumor growth and promotes lung and liver metastasis by recruiting MDSCs to produce IL-13 in a mouse model of breast cancer, acute promyelocytic leukemia (APL), and prostate cancer." (PMID 32117199, 2019). "IL-13Ra2 has a critical role to mediate the anti-tumor effect of IL-13 in breast cancer models." (PMID 26993600, 2016).
breast carcinoma (continued). "Furthermore, IL13Ralpha2 silencing was associated with enhanced IL-13-mediated phosphorylation of signal transducer and activator of transcription 6 (STAT6) and impaired migratory ability of metastatic breast cancer cells." (PMID 26208975, 2015). "Subsequent gene expression profiling of metastatic breast cancer cells proficient or deficient in IL13Rα2, and treated with or without IL-13, identified a subset of genes regulated by the IL-13 signaling pathway." (PMID 26208975, 2015). "In another study, “protumor” M2-polarized macrophages in the microenvironment of breast cancer were augmented after IL-13 administration, which further mediated tumor radioresistance; however, inhibition of IL-13-mediated M2 polarization of macrophages by PM37 could prevent radioresistance." (PMID 38264648, 2023). "both indicated that IL13 could promote metastasis of breast cancer cells to lung tissue." (PMID 35844536, 2022). "However, it remains unclear whether activating ILC2s would mediate similar antitumor effects in lung metastasis of breast cancer, since MDSCs are activated via IL-13/IL-13Rα1 signaling to induce pro-tumor effects." (PMID 35805039, 2022). "Because decreased TP63 levels have been associated with enhanced invasion and migration as well as metastatic potential of cancer cells, we hypothesized that, upon IL13Rα2 knockdown, IL-13 signaling suppresses metastasis by impairing the ability of breast cancer cells to migrate." (PMID 26208975, 2015). "By using PMA, IL-4, and IL-13, we successfully induced THP-1 cells into M2-like macrophages, which subsequently promoted breast cancer cell proliferation and inhibited apoptosis, accompanied by increased JMJD3 expression." (PMID 41955245, 2026). "Studies in breast cancer models revealed that these CD4 + T cells accelerate tumor development through secretion of IL-4 and IL-13." (PMID 38557942, 2024). "In contrast, the chronic inflammatory IL signature, including IL-4, IL-5, IL-10, IL-13, IL-17, and CXCL1, showed a significant prognostic effect across the whole cohort of breast cancer patients." (PMID 39456897, 2024). "Similar to our findings in vitro, other investigators have reported the signaling mediated by IL-13/IL-13Rα2 via AP-1 pathways in GBM and other tumor cell lines such as breast cancer, certain types of lung cancer cell line." (PMID 30572904, 2018). "Consistent with the role of IL-13 in the activation of MQ and MDSC, the up-regulation of IL-13 could be related to the defined role of MQ and MDSC in breast cancer progression." (PMID 39877637, 2025). "A cross-sectional study on depression in patients with breast cancer identified that the level of IL-13 was lower in the depressed group than in the non-depressed, a lack of further research to clarify the pathological mechanisms." (PMID 38426163, 2024). "No heterogeneity was found by breast cancer subtypes, except for IL-13 (Phomogeneity = 0.04) suggesting a significant positive association with breast cancer risk limited to the ER+PR±HER2+ subtype." (PMID 35430795, 2022). "Anti-inflammatory cytokines such as IL-4, IL-13, and TGF-β may polarize macrophages into M2 phenotypes which are considered immunosuppressive and can contribute to breast cancer progression by promoting growth, metastasis, and angiogenesis." (PMID 29849939, 2018). "In pulmonary metastatic model of breast cancer, Th2 CD4+ T lymphocytes that produce IL-4 and IL-13, M2-type TAMs and IMCs are activated and in turn produce EGF, thus resulting in activation of a paracrine-mediated enhancement of malignant cell invasion and dissemination." (PMID 27533463, 2016).
breast carcinoma (continued). "Here, we speculate that the immunosuppressive activity of MDSCs was induced by Arg1, rather than iNOS, through IL-13/IL-13Rα1 signaling in breast cancer lung metastasis." (PMID 35805039, 2022). "However, no clear relationship between IL-13 levels and poor outcome in breast cancer patients has been described." (PMID 35062739, 2022). "This was due to secretion by CD4+ T cells of pro-tumor Th2 cytokines (i.e., mainly IL-10 and IL-13), possibly with activation of CD4+ NKT and myeloid suppressive cells, and tumor-derived CCL17 that in turn recruited Tregs already described to have a pro-metastatic role in breast cancer." (PMID 33042121, 2020).
glioma (64 papers, 2010 to 2025). A benign or malignant brain and spinal cord tumor that arises from glial cells (astrocytes, oligodendrocytes, ependymal cells). "In fact, in our study, IL13 rs20541 was positively associated with the risk of PCa, whereas it was previously reported to be associated with a decreased risk of glioma." (PMID 37108754, 2023). "Alternatively, glioma tumor cells produce IL-13, which in turn caused autocrine activation of cell signaling through AP-1 pathway by engaging IL-13Rα2 chain." (PMID 30572904, 2018). "Thus, a meta-analysis conducted by Chinese scientists showed an association between the IL-13 rs20541 (R130Q) gene polymorphism and susceptibility to glioma, as the GA genotype was much more common in glioma patients." (PMID 35629280, 2022). "For instance, IL-13 or IL-4 cytokines fused to bacterial toxins can direct cytotoxic payloads to glioma cells overexpressing IL-13Rα2 or IL-4R." (PMID 40918539, 2025). "Few studies have characterised IL-13 expression in gliomas with the majority of research focused on the IL-13 receptor subunit alpha-2 (IL-13Rα2), which was shown to be aberrantly expressed in almost 80% of glioblastoma samples." (PMID 41034696, 2025). "loaded Dp44mT onto PEGylated PLGA NPs modified with the glioma‐targeting ligand interleukin 13 (IL13)." (PMID 38708806, 2024). "In particular, monoclonal antibodies specific for IL-13Rα2, which disrupt IL-13/IL-13Rα2 interactions, improved the survival of mice with orthotopic glioma xenografts and inhibited liver metastasis of colorectal cancer cells expressing IL13Rα2." (PMID 39598436, 2024). "Therapeutic agents labeled with IL-13 and other immunotherapies targeting IL13Ra2 have shown promise in the treatment of gliomas." (PMID 38201655, 2024). "Oncolytic measles virus strains, exhibiting anti-glioma activity after IL-13 modification, demonstrate significant cytotoxicity with enhanced specificity." (PMID 38201655, 2024). "Variations in genes involved in DNA repair, cell cycle, metabolism, and inflammation pathways have been recognized as a key basis of inherited glioma susceptibility, such as PRKDC, XRCC1, PARP1, ERCC1, ERCC2, EGF, and IL13." (PMID 36733406, 2023). "The DEGs were enriched in some Glioma-related processes, including “regulation of ion transport”, “interferon-gamma signaling”, and “interleukin-4 and interleukin-13 signaling”." (PMID 36138874, 2022). "CARs using IL13 mutants for targeting IL13Rα2 have previously shown efficacy in both preclinical (8, –10) and clinical glioma." (PMID 35939683, 2022). "Since then, a diverse set of biomarkers have been implicated as prognostic indicators in gliomas, including checkpoint molecules (PD-1, CTLA-4, TIM-3), growth/angiogenesis proteins (EGFR), and cytokines (TGF-β, IL-4, IL-13)." (PMID 35203944, 2022). "In this regard, GM-CSF, which is expressed at high levels in human gliomas, induces the upregulation of IL-4Rα on glioma-infiltrating MDSCs, thereby leading to IL-13-induced production of arginase resulting in T cell inhibition." (PMID 34948178, 2021). "For treating human glioma xenografts in rats, single intracranial injections of IL-13 “designer T cell” into tumor sites significantly increased survival." (PMID 33450900, 2021). "successfully synthesized carboxyl functionalized Gd3N@C80 to conjugate with targeting peptide, interleukin-13 (IL-13), for specific imaging of glioma cells in vitro." (PMID 33941206, 2021). "In this particular study, TTP inversely correlated with IL-13 levels in glioma tissues and TTP inhibited the growth, migration, and invasion of glioma cells through downregulation of IL-13 and attenuation of the PI3K/Akt/mTOR pathway." (PMID 32545247, 2020). "IL13-PE38QQR, a recombinant cytotoxic chimera of human interleukin 13 and the enzymatically active portion of pseudomonas exotoxin A, has been shown to target glioma cell lines in preclinical studies." (PMID 33050158, 2020).